MPPE1 (metallophosphoesterase 1)
Description:
Metallophosphoesterase that catalyzes the removal of a side-chain ethanolamine-phosphate (EtNP) from the second mannose of the GPI-anchor protein intermediate. Participates in the glycan remodeling steps of GPI-anchor maturation to allow an efficient transport of GPI-anchor proteins from the endoplasmic reticulum to the Golgi.
Synonyms: PGAP5; Cdc1
Tractability: Antibody: UniProt predicts a signal peptide or a membrane-spanning region. PROTAC: ubiquitination databases record sites on it; its protein half-life has been measured.
Gene: Protein-coding gene on chromosome 18 (11,882,622 to 11,909,180, reverse strand). Ensembl gene ENSG00000154889.
Subcellular location: Endoplasmic reticulum-Golgi intermediate compartment membrane
Subcellular location (Human Protein Atlas): Golgi apparatus; Nucleoplasm
Gene Ontology:
Molecular function: protein binding; GPI-mannose ethanolamine phosphate phosphodiesterase activity; manganese ion binding; hydrolase activity; phosphoric diester hydrolase activity
Biological process: GPI anchor biosynthetic process; endoplasmic reticulum to Golgi vesicle-mediated transport
Cellular component: endoplasmic reticulum-Golgi intermediate compartment membrane; Golgi apparatus; endoplasmic reticulum exit site; cytoplasm; endomembrane system; endoplasmic reticulum-Golgi intermediate compartment
Genetic constraint (gnomAD): Loss-of-function variants: 22 observed, 30.51 expected, observed/expected ratio (o/e) 0.72, 90% interval 0.51 to 1.03. The upper end of that interval is the gene's LOEUF score, 1.03, which puts it in group 4 of 6, group 1 being the genes least tolerant of losing a copy. Missense variants: 329 observed, 367.79 expected, observed/expected ratio (o/e) 0.89, 90% interval 0.82 to 0.98. Synonymous variants: 126 observed, 146.04 expected, observed/expected ratio (o/e) 0.86, 90% interval 0.75 to 1.
Homologues: Orthologues: chimpanzee MPPE1 (99% identical), macaque MPPE1 (94% identical), rabbit MPPE1 (77% identical), pig MPPE1 (75% identical), mouse Mppe1 (74% identical), rat Mppe1 (73% identical), guinea pig MPPE1 (61% identical), tropical clawed frog mppe1 (57% identical), zebrafish mppe1 (53% identical), Drosophila melanogaster PGAP5 (38% identical), Caenorhabditis elegans mppe-1 (33% identical).
Diseases named in the same sentence as MPPE1 in open-access papers:
MPPE1 is named in the same sentence as 132 diseases in open-access papers, as found by Europe PMC text mining. Sharing a sentence is not in itself a finding about the gene and the disease. The quoted sentences say what the papers report.
Atrophy (1 paper, 2022). Any weakening or degeneration, especially through lack of use. "Striatal atrophy and gliosis may be sequelae of status dystonicus with multiorgan failure, but the influence of mutant MPPE1 and SLC6A7 cannot be excluded." (PMID 35876425, 2022).
mental disorder (1 paper, 2022). A disease that has its basis in the disruption of mental process. "Eight genes are implicated in viral (SEC14L1, JMJD6, SRSF2, TMPRSS2, MX1, MX2) or bacterial (COL8A1, SPIRE1) infections, seven genes (MFSD11, METTL23, CTTNBP2, BACE2, IMPA2, MPPE1 and GNAL) are involved in mental disorders and one gene (MGAT5B) is related to the Golgi complex." (PMID 35581286, 2022).
infection (54 papers, 2017 to 2025). The state of being infected such as from the introduction of a foreign agent such as serum, vaccine, antigenic substance or organism. "Although Leptospira was the infection with more genes found in the significant genomic window, few genes are linked to each other (IMPA2, MPPE1, and GNAL—TAF5 and USMG5)." (PMID 35581286, 2022).
movement disorder (1 paper, 2022). Neurological conditions resulting in abnormal voluntary or involuntary movement, which may impact the speed, fluency, quality and ease of movement. "In conclusion, we have identified variants in MED27, SLC6A7, and MPPE1 in a family with a complex and severe neurodevelopmental condition associated with a life‐threatening movement disorder." (PMID 35876425, 2022).
neurological disorders (1 paper, 2022). "Indeed, identified genes are implicated in viral (SEC14L1, JMJD6, SRSF2, TMPRSS2, MX1, MX2) bacterial (COL8A1, SPIRE1), and neurological disorders (MFSD11, METTL23, CTTNBP2, BACE2, IMPA2, MPPE1 and GNAL), or in the functions of the Golgi complex (MGAT5B), organelle where viral envelope is occurred." (PMID 35581286, 2022).
MPPE1 also shares sentences with these, for which no sentence is quoted: tumor (411 papers); cancer (99); melanoma (56); breast cancer (22); viral infection (15); lung carcinoma (11); pancreatic cancer (8); Autoimmunity (7); influenza (7); COVID-19 (6); glioblastoma (6); osteosarcoma (6); asthma (5); breast tumors (5); colitis (5); colon cancer (5); head and neck squamous cell carcinoma (5); Listeria monocytogenes infection (5); lung adenocarcinoma (5); Obesity (5); hepatocellular carcinoma (4); malaria (4); non-small cell lung carcinoma (4); atherosclerosis (3); autoimmune disease (3); bacterial infection (3); cryptococcal infection (3); fibrosarcoma (3); HIV-1 infection (3); inflammatory liver disease (3).
A further 97 diseases each share a sentence with MPPE1 in 3 papers or fewer.